BRCA1 (BRCA1 DNA repair associated)
Diseases named in the same sentence as BRCA1 in open-access papers (continued):
Sharing a sentence is not in itself a finding about the gene and the disease.
cancer (continued). "Therefore, the synthetic lethal relationship based on PARP1 inhibition could be applied to CDK12 mutants, similar to its application to BRCA1 mutants, and CDK12 inhibition might provide a rationale for the use of combination therapy with a PARP inhibitor in CDK12 mutation-related cancers." (PMID 32451425, 2020). "Most patients interpret their BRCA1/2 VUS as meaning there is some predisposition for cancer, despite recalling they were told the result is “noninformative.”25 Coldspot information could be used to avoid this problem by reducing the number of variants classified as VUS." (PMID 31911673, 2020). "In women with BRCA1/2 PV/LPVs, bilateral RRM and bilateral RRSO have been demonstrated as effective measures to prevent cancer." (PMID 32046255, 2020). "In fact, a BRCA2 -/- genetic background or depletion of either BRCA1 or RAD51 confers a higher sensitivity to PDS in HCT116, DLD1 and HEK293T cancer cell lines." (PMID 32098397, 2020). "To this end, we aimed to investigate the prevalence of germline PVs in BRCA1/2-negative TNBC patients in Cyprus, unselected for family history of cancer or age of diagnosis." (PMID 33120919, 2020). "Several reports suggest that alternative splicing of specific genes, such as BRCA1, BRCA2, BARD1, or ERCC1, can impact on the response of cancer cells to PT and some studies also suggest that this correlates with PT resistance in human cancer." (PMID 32332923, 2020). "Collectively, these results establish USP9X as a deubiquitinase for BRCA1 and reveal a previously unrecognized role of USP9X in the regulation of HR repair and the sensitivity of cancer cells to DNA‐damaging agents." (PMID 31512408, 2019). "Germline and somatic mutations in genes that promote homology-directed repair, especially BRCA1 and BRCA2, are frequently observed in several cancers, in particular, breast and ovary, but also prostate and other cancers." (PMID 31186630, 2019). "Further in S-phase cells RIF1 is gradually competed out from 53BP1 by the protein Suppressor of Cancer cell Invasion (SCAI), which binds 53BP1 to allow BRCA1-mediated repair." (PMID 31552267, 2019). "Increasing BRCA1 and BRCA2 (collectively termed herein as BRCA) gene testing is required to improve cancer management and prevent BRCA-related cancers." (PMID 31125106, 2019). "Finally, in tested individuals with no information about personal/family history of cancer, a clinically significant variant was identified in 14.2% (18/127) of the cases with 9.4% (12/127) in BRCA1/2 genes and 4.7% (6/127) in other high, moderate and low risk genes." (PMID 31159747, 2019). "However, even for women with the BRCA1 mutation, none are likely to get cancer before age 20, and 28% of them may never get cancer." (PMID 30700767, 2019). "Firstly, CpG islands in promoter regions of various tumor suppressor genes (TSGs), such as p16INK4A, p73, BRCA1, and TIMP3, are hypermethylated in cancer, inhibiting their expression and, thus, leading to uncontrolled proliferation of cancer cells." (PMID 30669400, 2019). "Since 2005, the U.S. Preventive Services Task Force has recommended screening for unaffected (i.e., no personal history of cancer) women with a strong family history of certain cancers to identify those who may be at increased risk for potentially harmful pathogenic variants in BRCA1/2." (PMID 31083288, 2019).
cancer (continued). "Detection of a BRCA1 or BRCA2 pathogenic variant triggers several clinical management actions, which may include increased surveillance and prophylactic surgery for healthy carriers or treatment with the PARP inhibitor therapy for carriers diagnosed with cancer." (PMID 31013702, 2019). "Reconstitution with the wild-type BRCA1 significantly (p < 0.0001) suppressed the clonogenic potential of HCC1937 cells, an important characteristics of cancer stemness." (PMID 31273285, 2019). "For example, a minority discussed the considerable uncertainty around secondary findings (e.g., what a BRCA1 pathogenic variant would mean in the absence of a personal/family history of cancer), or that participants could opt in or opt out if they later changed their minds." (PMID 30270361, 2019). "This rise was due to alterations at a low percentage in genes with proven predictive value in the context of approved anti-cancer drugs (e.g., EGFR, BRAF, ERBB2, BRCA1, BRCA2, RET, ALK) in all cancer types." (PMID 29544535, 2018). "Hundreds of FOXP3 target genes have been identified in both Treg cells and cancer cells so far, including HER2/ERBB2, SKP2, CD44, BRCA1, p21, and LATS2." (PMID 30011797, 2018). "Based on the mechanism of PARP1-H2AX-BRCA1/2, recent study has focused on PARP1 as a possible therapeutic target for various human malignant tumors, especially in carcinomas have defects in BRCA1/2." (PMID 29784019, 2018). "Therefore, regarding the application of PARP inhibition, our results suggest that more cases of cancers might benefit from PARP inhibition therapy because a substantial number of cases are included in the poor-prognostic group by expressing PARP1/γH2AX/BRCA1/2." (PMID 29784019, 2018). "Poly(ADP‐ribose) polymerase (PARP) inhibitors (PARPi) are effective in cancers with defective homologous recombination DNA repair (HRR), including BRCA1/2‐related cancers." (PMID 30377213, 2018). "Thus, the role of Akt-mediated BRCA1 phosphorylation for DNA repair remains controversial and more studies are needed to gain a better understanding of the interaction between Akt and BRCA1 and its influence on DNA repair and the fate of irradiated cancer cells." (PMID 29562639, 2018). "Here, we genetically ablated PARP1 in a BRCA1- and BRCA2-positive cancer cell line, HCT116, to better understand the role of PARP1 in an otherwise normal, albeit oncogenic, generic background." (PMID 30410680, 2018). "Intriguingly, the delivering women had 26% lower BRCA1 and MGMT methylation frequencies than those of the cancer-free female subjects." (PMID 30049288, 2018). "CpG methylation in promoter regions of tumor-suppressor genes (e.g., BRCA1, VHL and p16Ink4a) leads to the inactivation of these cancer-preventing proteins." (PMID 30249004, 2018). "In this study, we investigated the prevalence of BRCA1 and MGMT promoter methylations in white blood cells (WBC) from cancer-free women and newborn females." (PMID 30049288, 2018). "In BRCA1 and BRCA2 carriers, the cancer prevalence (and incidence) is much higher than in the cohort studied here (approximately 6-fold higher) and the use of MRI as a screening tool can be justified." (PMID 28265306, 2017). "Consistent with previous studies, patients harboring germline BRCA1 mutant tumors had a worse TTP (p=0.023) and shorter OS (p=0.007) to PARP inhibitor monotherapy compared to patients with germline BRCA2 mutant cancers in our series of patients." (PMID 29262651, 2017). "Essential components of HR are the tumor suppressor proteins BRCA1 and BRCA2, since their absence results in unrepaired lesions, cell-cycle arrest and cell death in cancer cells exposed to cytotoxic chemotherapy." (PMID 28482906, 2017). "BRCA1 and BRCA2 are two classic tumor suppressor genes that play important roles not only in tumorigenesis but also cancer progression and outcome." (PMID 28415599, 2017).
cancer (continued). "For example, in the recent paper by the Toronto group of 496 BRCA1 and BRCA2 carriers, 57 cancers were identified in 1847 screening rounds (31 per 1000) compared to 26 cancers in 5319 screening rounds (5 per 1000) in the present study." (PMID 28265306, 2017). "Together with previous reports of VPA augmented radiation-induced apoptosis through targeted activity on BRCA1, Rad51 and Ku80 proteins, this study advanced the proposal for the use of VPA as a neoadjuvant to radiotherapy for cancer treatment." (PMID 28489060, 2017). "BRCA1 plays a critical role in homology-directed repair (HDR) of DNA double strand breaks, and the repair defect of BRCA1-mutant cancer cells is being targeted with platinum drugs and poly (ADP-ribose) polymerase (PARP) inhibitors." (PMID 28398198, 2017). "Integrated analysis of the DNA methylation and mRNA expression data showed that 98 genes were silenced by DNA methylation, including genes that have been involved in the development of cancers, such as ZFP82, PARP6, BRCA1 and MGMT." (PMID 29156578, 2017). "Besides germline BRCA1/2-mutant cancers, there has been increasing evidence that PARP inhibitors may have a role in somatic BRCA1/2-mutant cancers, or cancers associated with HR deficiency, and more recently, possibly even tumors deficient in chromatin regulation like cancers with ARID1A mutations." (PMID 28829366, 2017). "Despite impressive clinical activity in patients with germline BRCA1 and BRCA2 (BRCA1/2) mutant cancers, antitumor responses to poly(ADP-Ribose) polymerase (PARP) inhibitors are variable." (PMID 29262651, 2017). "The change in expression of BRCA1, GSTP1, PTEN, and others have been widely documented in various types of human cancers." (PMID 28199384, 2017). "Considering the fact that β-hCG is an immune suppressor and is overexpressed in BRCA1 defective cancer cells, inhibiting β-hCG could be a better treatment strategy with immense clinical application than using immune modulators for reducing the growth of such cancers." (PMID 28869585, 2017). "To date, genetic testing of BRCA1 and BRCA2 is conducted in clinical practice only, in individuals with a strong family history or after a cancer diagnosis." (PMID 29275340, 2017). "The normal function of BRCA1 and BRCA2 genes is DNA repair, transcription and recombination, all of which prevent cancer development as part of the tumor suppressor group of genes." (PMID 29021639, 2017). "However, not all changes in BRCA1 gene cause the protein to become faulty or lead to cancer." (PMID 28398198, 2017). "Beyond BRCA1/2, anti-tumor activity of PARP inhibitors was also reported in sporadic (BRCA1/2 wild type) cancers with BRCA-like phenotype." (PMID 28055979, 2017). "Switching on and off of an array of genes such as BRCA1, BRCA2, Akt1, ERCC1 and ABCB1 were identified to modulate sensitivity toward chemotherapy in cancer patients." (PMID 27980217, 2017). "BRCA1 and BRCA2 are involved in homologous recombination (HR) DNA repair and are germ-line cancer pre-disposition genes that result in a syndrome of hereditary breast and ovarian cancer (HBOC)." (PMID 29021619, 2017). "The aim of the present study was to evaluate analytical sensitivity and specificity of the Counsyl Inherited Cancer Screen (ICS), an NGS-based test for BRCA1/2 testing." (PMID 27375968, 2016). "Some important cancer genes, such as PIK3CA, BRCA1, BRCA2, and ERBB2, show a mixture of amplifications and deletions." (PMID 27556158, 2016). "For further exploration, we selected five genes that have been previously experimentally demonstrated in other cancer setting in humans, CXCL8/IL8, UHRF1, BRCA1, MCM10, and CDKN3." (PMID 26859141, 2016). "This pathway is a genetic disease about DNA repair genes–BRCA1, RAD51, PMS2 and FANC proteins–which are higly related to cancers." (PMID 27883053, 2016).
cancer (continued). "In the context of BRCA1 and BRCA2 mutation carriers, it has been shown that other factors such as single nucleotide polymorphisms (SNPs) in genes from other DNA repair pathways could cause a higher genomic instability, hence increasing the cancer risk predisposition." (PMID 27015555, 2016). "Also ROS inducers like PB could reduce BCSCs in BRCA1 defective cancers." (PMID 27229859, 2016). "We also examined sensitivity of BRCA1-mutant cells to olaparib, a PARP inhibitor used in BRCA-mutant cancers to take advantage of synthetic lethality with the homologous repair defect." (PMID 27708239, 2016). "Their analysis identified copy number variation in BRCA1 and BLM, two genes found to be critical nodes in our sub-networks, as factors related to sensitivity to metformin in cancer tissue." (PMID 26841718, 2016). "However, “Carrying the mutation” is indeed not good news, it at least provides a solid reason for having cancer.BRCA1/2 mutation carriers may worry about the recurrence of cancer and do not want to go through the painful process once again." (PMID 27428375, 2016). "What is clear is that BRCA1/2 mutations do not per se reflect a defect in HR, and that functional testing of HR capacity may be required to reliably classify the DNA repair defect in cancers." (PMID 25852742, 2015). "While we found significantly decreased expression of multiple NHEJ and HR repair proteins in HPV+ HNSCC cell lines, BRCA1 and RAD51, two key HR proteins often identified as the culprits in other HR-defective cancers, appear relatively unaffected." (PMID 26336991, 2015). "When the sera from cancer patients were tested for the presence of autoantibodies to PARP1 and BRCA1/BRCA2, the autoantibody responses slightly decreased and the positive autoantibody reactions varied from 0% to 50.0%." (PMID 25865228, 2015). "BRCA1- and BRCA2-mutant cancers exhibit differences in histopathology, gene expression profiles, and clinical course, even though they share similarities in their marked levels of genomic instability." (PMID 25699710, 2015). "Two other genes (BRCA1 and ESR1) displayed very small changes in the extent of methylation (<2 % differential for cancer vs. adjacent tissue)." (PMID 26510686, 2015). "Nevertheless, despite the overlapping biological mechanisms of the FA and BRCA1 pathways in DT40 and human cells, the clinical relevance of these findings in cancer should be treated with caution." (PMID 26324327, 2015). "The antibody responses to PARP1, BRCA1, and BRCA2 had strong reactivity in representative cancer sera compared to normal controls." (PMID 25865228, 2015). "BRCA1-associated cancer is age-dependent, and whether or not this is stochastic or influenced by other factors (modifiers of penetrance) is a question that has not been fully explored: Both stochastic elements and modifying factors may be instrumental in diseases causation." (PMID 26052370, 2015). "ABCB1, BRCA1, GSTP1, and IGF2 displayed both an increased CM fraction and hyper-methylation in cancer." (PMID 26659027, 2015). "It is important to note that because family members share a quantity of their genes and often their environment, it is possible that the large number of cancer cases present in these families may be due in part to other genetic or environmental factors rather than possessing a BRCA1/2 gene mutation." (PMID 26236408, 2015). "Particularly, there were 88 DEGs (hypergeometric P = 0.0019) that overlap with the known cancer genes, including PDAC related genes such as MYC, BRCA1, and KRAS, which indicates that the DEGs of this study have close bond with the cancer progression indeed." (PMID 26425543, 2015). "Consistent with increased intrachromosomal rearrangements in SPOP mutant cancers, in vivo data nominated a functional role for SPOP in DSB repair, similar to BRCA1." (PMID 26374986, 2015).
cancer (continued). "In carcinomas from Patients A, G and M with high HRD scores, BRCA1 and/or BRCA2 mRNA were markedly downregulated by RNA-sequencing analysis and qRT-PCR (data not shown)." (PMID 25916844, 2015). "For example, carcinomas from Patients C and G appear to cluster together and both have high HRD score, low BRCA1 expression and BRCA1 LOH." (PMID 25916844, 2015). "Several recent publications suggest that pharmacological targeting of BRCA1 and BRCA2 can sensitize BRCA-wildtype cancers to platinum-based chemotherapy and PARP inhibition." (PMID 24624361, 2014). "Given that BRCA1 and BRCA2 participate in the repair of DNA double strand breaks, here we have investigated whether variations, Single Nucleotide Polymorphisms (SNPs), in genes participating in other DNA repair pathway may be associated with cancer risk in BRCA carriers." (PMID 24698998, 2014). "To further appreciate the link between BRCA1 promoter methylation in WBC and breast carcinogenesis we searched for BRCA1 methylation in WBC from cancer-free women." (PMID 25403427, 2014). "However, it is not clear whether the effect was due to the BRCA1/2 mutation status or their cancer status, or indeed previous cancer treatment, as both chemotherapy and radiotherapy have been shown to affect TL." (PMID 24489760, 2014). "This review summarizes recent findings of the function of BRCA1 and PTEN involved in genomic stability and cancer cell signaling." (PMID 25426449, 2014). "Notably, the knowledge of founder BRCA1 or BRCA2 mutations may provide more precise estimates of the prior probability of carrying a mutation in either genes and of the likelihood of a mutation carrier developing cancer." (PMID 24516540, 2014). "As part of the DDR, BRCA1 is phosphorylated by CHEK2 and ATM in normal cells and cancer cells following irradiation or exposure to alkylating agents [reviewed in Ref." (PMID 24624361, 2014). "Systematic comparisons of gene expression profiles have revealed that BRCA1 regulates expression of a wide range of genes in human prostate (DU-145) and breast (MCF7) cancer cells." (PMID 24704793, 2014). "Moreover, BRCA1 mRNA downregulation could be rescued by depleting Dicer and Drosha, and in non-cancer cells partial reduction in BRCA1 transcript levels could be achieved with ectopic transcription of double stranded SINE RNA with sequence identity to the BRCA1 transcript." (PMID 24705161, 2013). "Specifically, VEGF was positive in 92% (24/26) of BRCA1-2 carriers, in 74% (42/57) of BRCAX and in 36% (25/70) of sporadic cancers." (PMID 23326384, 2013). "For example, TS genes involved in DNA repair such as BRCA1, MLH1 and MGMT show promoter hypermethylation in human cancers." (PMID 23472065, 2013). "MVD was high in 61% (16/26) of BRCA1-2 carriers, in 51% (28/55) of BRCAX and in 53% (39/74) of sporadic cancer tissues." (PMID 23326384, 2013). "For example, the RNA splicing and processing theme involves 2,009 pSNVs in 652 genes, including 38 known cancer genes such as BRCA1, RBM15, CDK12, CDC73 and TOP1 (FDR p = 1.3e − 06, Fisher's exact test), as well as candidate cancer genes." (PMID 24089029, 2013).